MMP14 (matrix metallopeptidase 14)
Diseases named in the same sentence as MMP14 in open-access papers (continued):
Sharing a sentence is not in itself a finding about the gene and the disease.
renal cell carcinoma (10 papers, 2006 to 2024). "For instance, circPTCH1 (hsa_circ_0139402) was reported to facilitate migration, invasion and metastasis in renal cell carcinoma (RCC) through modulating miR-485-5p/MMP14 signaling pathway." (PMID 38177102, 2024). "For instance, the overexpression of MMP-2 on the surface of renal cell carcinoma and membrane-type MMP-14 activity directly led to MICA shedding." (PMID 34502191, 2021). "Therefore, it seems that MMP-14 could be a promising target in the diagnosis, prognosis and therapy of renal cell carcinoma." (PMID 39125675, 2024). "The aim of this study was to evaluate the expression, content, and activity of selected membrane-type metalloproteinases (MMP-14 and MMP-15) in human renal cell carcinoma." (PMID 39125675, 2024). "Therefore, the aim of this study was to evaluate the expression, content and activity of MMP-14 and MMP-15 in human renal cell carcinoma." (PMID 39125675, 2024). "MMP-14 appears to play a more significant role than MMP-15 in renal carcinoma, suggesting it could be a promising target for diagnosis, prognosis, and therapy in renal cell carcinoma." (PMID 39125675, 2024). "Transmembrane metalloproteinases MMP-14, MMP-15 and MMP-16 have been found to be significantly expressed in tumor-transformed tissue in renal cell carcinoma and to be present in urine samples from the same patients; however, no reports have been published on their expression in renal cell carcinoma." (PMID 39125675, 2024). "Likewise, in vitro experiments demonstrated that MMP-14 and HIF-2α are overexpressed in metastatic renal cell carcinoma (RCC) cells, which synthesized a truncated non-functional pVHL protein." (PMID 38069210, 2023).
Stroke (10 papers, 2012 to 2024). Sudden impairment of blood flow to a part of the brain due to occlusion or rupture of an artery to the brain. "Of note was the persistent upregulation of the Mmp12 gene encoding a metalloelastase and Mmp14 encoding a collagenase secreted by fibroblasts in the infarcted area of aged rats at 2 weeks post-stroke." (PMID 24672479, 2014). "In fact, MMP-14 overexpression was also noticed in disorders with a strong neuroinflammatory component in their pathogenesis, such as multiple sclerosis or stroke, further pointing to a link between regulation of MMP-14 and neuroinflammation." (PMID 28993312, 2017). "During the recovery phase, however, MMP14 could play an important pro-angiogenic role and promote tissue recovery after stroke." (PMID 24672479, 2014). "However, one third of the genes were increased with suboptimal timing in aged rats, either on day 3 post-stroke (Adam17, Gpc3, Mmp14, Nid2, Tagln, Wnt5b) or on day 14 after stroke (Col4a2, Col8a1, Cthrc1, Cxcl1, Gpc3, Tgfbr2)." (PMID 23251410, 2012). "Furthermore, female MMP-3 KO stroke brains showed decreased expression of apoptosis signaling genes Casp6, Tnfrsf1b, Tnfrsf1a, and Tnf, and downregulated expression of matrix metalloprotease genes Mmp14, Mmp9, and Mmp11." (PMID 39000490, 2024). "Therefore inhibiting Adam 17 and Mmp14 geneproducts by available compounds may increase the chance of increased angiogenesis and hence a better tissue restoration in aged brains after stroke." (PMID 23251410, 2012). "Importantly, GWAS have associated variants of several of the gene targets of miR-24-3p;FAF1, GATA3, MMP14, NOS3 and PTPRF with stroke." (PMID 36613546, 2022).
COVID-19 (9 papers, 2021 to 2025). A disease caused by infection with severe acute respiratory syndrome coronavirus 2. "Although matrix metallopeptidase (MMPs) are proteolytic enzymes responsible for extracellular matrix protein degradation, in our study matrix metalloproteases such as MMP23B, MMP15 and MMP14 were downregulated in COVID-19 diseased lungs compared with expression in lungs of uninfected controls." (PMID 33674719, 2021). "Single-cell analysis of COVID-19 lungs revealed coexpression of CD13 and MMP14 by various cell types, and higher CD13 expression compared with controls." (PMID 40168094, 2025). "Immunostaining of lung samples from patients with COVID-19 reveals high CD13 expression, which, along with the potential coexpression with MMP14, suggests that epithelial cells and macrophages could be primary sources of sCD13." (PMID 40168094, 2025). "Since we had evidence of increased expression of MMP-14 and MMP-7 in COVID-19 lung tissue by proteomics reanalysis, both described activation pathways that could be effective in TAF samples to produce active-MMP-2 and active-MMP-8." (PMID 35625532, 2022). "This target proteomics approach indicated that MMP-2, MMP-7, MMP-8, and MMP-14 figured out the COVID-19 perturbation with a significant increase compared to non-COVID-19 individuals." (PMID 35625532, 2022). "It appears partly reasonable with our results from proteomics reanalysis, which showed a significant increase in detection of MMP-2, MMP-7, MMP-8, and MMP-14, but not the expression of the MMP-9 protein, in lung tissue from COVID-19 compared to non-COVID-19 subjects." (PMID 35625532, 2022).
Insulin resistance (8 papers, 2013 to 2025). Increased resistance towards insulin, that is, diminished effectiveness of insulin in reducing blood glucose levels. "Among them, MMP-2, MMP-9, and MMP-14 are particularly important due to their links with systemic inflammation, insulin resistance, and vascular complications." (PMID 41227041, 2025). "Furthermore, MMP-14 was found to be overexpressed in obese adipose participating in abnormal lipid metabolism and insulin resistance." (PMID 32214011, 2020).
invasive breast carcinoma (8 papers, 2006 to 2021). A carcinoma that infiltrates the breast parenchyma. "The cancer suppressor protein kinase D1 (PKD1), a repressor of different MMPs, including MMP14, is highly expressed in normal breast tissue, but epigenetically silenced by DNA methylation in invasive breast cancer, where MMP14 and other MMPs are induced." (PMID 31466240, 2019). "A three-step immunohistochemical method was applied to paraffin-embedded sections from 154 patients with invasive breast carcinoma in order to detect expressions of the proteins EGFR, pEGFR, oestrogen receptor, progesterone receptor, c-erbB-2, pAkt, VEGFR-1/Flt-1, MMP-14 and uPAR." (PMID 18522728, 2008).
lung fibrosis (8 papers, 2017 to 2022). "In summary, the current study demonstrated that epithelial deficiency of MMP14 exacerbates bleomycin-induced experimental lung fibrosis and impair remodeling resolution." (PMID 33805743, 2021). "Previous studies in our lab showed that MT1-MMP (Mmp14) is increased in bleomycin-induced lung fibrosis and in IPF the enzyme is localized mainly in the alveolar epithelium." (PMID 33805743, 2021). "In this study, the role of Mmp14 was explored in experimental lung fibrosis induced with bleomycin in a conditional mouse model of lung epithelial MMP14-specific genetic deletion." (PMID 33805743, 2021). "In this article, we discovered that MMP14 was controlled and regulated by Nogo-b and was correlated to pulmonary fibrosis." (PMID 29050340, 2017). "Among these candidate genes, MMP14 was selected as our target gene for further study, for it is considered to be the gene most likely to be correlated to pulmonary fibrosis and it has validated as the greatest differential expression genes in the list." (PMID 29050340, 2017). "Our study demonstrated that MMP14 played a critical role in EMT of pulmonary fibrosis, and the expression level of MMP14 determined the progress of EMT." (PMID 29050340, 2017). "In conclusion, MMP14/Nogo-b pathway serves as a new driver factor of the EMT process in BLM-induced pulmonary fibrosis, which can intensify EMT of cells by stimulating release of free TGF-β1." (PMID 29050340, 2017). "Likewise, increased protein expression of MMP14 has been observed in epithelial cells of bleomycin-induced lung fibrosis." (PMID 33805743, 2021). "To confirm whether MMP14 would also affect the pulmonary fibrosis through EMT in human, we performed MMP14 over-expression and knockdown experiments in A549 cell." (PMID 29050340, 2017). "In all, the obtained results demonstrated that MMP14 as a new downstream target of Nogo-b could mediate the promote pulmonary fibrosis, in addition, Nogo-b/MMP14 could regulate pulmonary fibrosis by affecting the process of cleaving TGFß proteinogens." (PMID 29050340, 2017). "Moreover, we discussed the correlation between Nogo-b and MMP14, both of which were molecules that could promote EMT and cause pulmonary fibrosis." (PMID 29050340, 2017). "Hence, we hypothesized that Nogo-b/MMP14 signaling pathway was affecting the process of pulmonary fibrosis by influencing the TGFβ1 signaling pathway." (PMID 29050340, 2017). "In addition, the therapeutic schedule specific to MMP14/Nogo-b may effectively relieve the symptoms of pulmonary fibrosis, which is the task our team plans to work on." (PMID 29050340, 2017). "MMP-14 is overexpressed in AECs of IPF lungs, mainly in hyperplastic cuboidal type 2 pneumocytes and bleomycin-induced lung fibrosis." (PMID 35805895, 2022). "Subsequently, we found that MMP14 abundant in extracellular matrix and TNF signaling pathway was significantly increased in the pulmonary fibrosis model induced by bleomycin via RT-PCR verification." (PMID 29050340, 2017). "All these results indicated that Nogo-b/MMP14 signaling pathway actually relied on the enhancement of enzyme cleavage of TGFβ precursor proteins rather than the influences on mRNA expression to affect the EMT of airway epithelial cell and pulmonary fibrosis." (PMID 29050340, 2017). "Furthermore, we show that DZNep treatment alone or in context of SARS‐CoV or SARS‐CoV‐2 infections reduces abundance of pulmonary fibrosis markers (e.g., SERPINE1, MMP14, and COL4A1) and increases levels of factors with antifibrotic activity (e.g., HOPX, PI3/ELAFIN, and SLPI)." (PMID 35833542, 2022).
pancreatic ductal adenocarcinoma (8 papers, 2016 to 2024). An infiltrating adenocarcinoma that arises from the epithelial cells of the pancreas. "For example, Snail overexpression in pancreatic ductal adenocarcinomas increases tumor cell invasiveness by increasing the expression of MMP-14 and membrane type (MT)-1-MMP." (PMID 26859575, 2016). "Altogether, our results suggested a new signaling axis of KrasG12D/CCL9/MMP14 and MMP3 to initiate pancreatic ductal adenocarcinoma through promoting ADM in the pancreas." (PMID 38731942, 2024). "It is also overexpressed in pancreatic ductal adenocarcinoma (PDAC), where its deletion reduces cell migration and invasion by downregulating MMP-2 and MMP-14." (PMID 39768218, 2024).
squamous cell carcinoma (8 papers, 1999 to 2025). A carcinoma arising from squamous epithelial cells. "In squamous cell and epidermoid carcinomas, MMP-14 expression is significantly increased, highlighting its role in the degradation of extracellular matrix components, thereby facilitating tumor invasion and metastasis." (PMID 40572725, 2025). "Our results reveal distinct expression patterns of MMP-14, Maspin, and β-catenin across oral potentially malignant disorders and squamous cell carcinoma, reflecting their roles in matrix remodeling, tissue homeostasis, and Wnt-driven oncogenesis." (PMID 40572725, 2025). "Niiya and colleagues identified BCAM as a substrate of MMP14 in human epidermoid carcinoma A431 cells to produce a cleavage product of unknown function." (PMID 36647260, 2023).
aneurysm (7 papers, 2015 to 2023). Bulging or ballooning in an area of an artery secondary to arterial wall weakening. "An adverse role for MMP-14 in aneurysm progression has been suggested given bone marrow transplantation of Mmp14-deficient macrophages into wild-type mice prevented AAA development in the peri-aortic CaCl2-application model." (PMID 37799778, 2023). "Knockout of VSMC MT1-MMP in apoE−/− (Mmp14−/−/apoE−/−) mice increased the size of atherosclerotic plaques and promoted the formation of aneurysm likely through promoting proinflammatory responses and enhancing smooth muscle proliferation." (PMID 34297054, 2021). "Numerous studies have demonstrated elevated amounts of MMP-14 mRNA after inducing aneurysms in animal models." (PMID 30794673, 2019). "Normalized levels of transcripts including MMP12, MT1-MMP (MMP14), and heme oxygenase increased after aneurysm development, particularly in the gene knockout mice, consistent with the invasion of inflammatory macrophages." (PMID 34617062, 2021). "Regression analyses showed that only the p-values of the regression coefficients in aneurysms < 5.5 cm depicted a linear relationship between active MMP-2 and TIMP-2 (p = 0.002), as well as between active MMP-2 and MMP-14/TIMP-2 ratio (p = 0.024)." (PMID 30794673, 2019). "Our ELISA results in the aneurysm group revealed that mean MMP-14 measured 3.55 ng/mL (SD 1,22) and mean TIMP-2 22.77 ng/mL (SD 7.99), whereas in the control group mean MMP-14 measured 3.71 ng/mL (SD 0.84) and mean TIMP-2 30.94 ng/mL (12.40)." (PMID 30794673, 2019). "Therefore, future working groups will need to investigate how, precisely, MMP-14 is regulated, as well as its activity in aTAA and role in MMP-2 activation at different stages of aneurysm development." (PMID 30794673, 2019). "This is another possible explanation for our finding that MMP-14 does not differ between aneurysms and controls at the time of surgery." (PMID 30794673, 2019). "We found only a significantly lower mRNA expression of MMP-2 in aneurysms, whereas higher expression of MMP-9 in aneurysms was not significant between the groups as well as the expression of MMP-1 and MMP-14." (PMID 26539497, 2015). "The local tissue's MMP-14/TIMP-2 ratio may regulate the degree of Pro-MMP-2 activation in human aTAA as a determining factor, but MMP-14 and TIMP-2 do not seem to be enzymatically essential to aneurysm development." (PMID 30794673, 2019). "The tissue's MMP-14/TIMP-2 ratio may regulate the degree of Pro-MMP-2 activation as a determining factor, while the enzymatic activities of MMP-14 and TIMP-2 do not seem to play a key role in aneurysm development." (PMID 30794673, 2019). "On the other hand, MMP-14, TIMP-2 and their ratio in ROC curve are negligible compared to that of MMP-2, enabling us to hypothesize that the enzymes that activate MMP-2 are not the determining enzymatic factor in aneurysm development, rather that they support the central role of MMP-2 activation." (PMID 30794673, 2019).
asthma (7 papers, 2015 to 2025). "Therefore, the OAE‐induced cleavage of CD100 by MMP14 in macrophages is a novel therapeutic target for treating asthma." (PMID 34414666, 2021). "Furthermore, based on described biological functions, it is reasonable to suppose that genes which are potentially associated with asthma symptoms may be located in this region, with the example of SLC7A7, MMP14 and DAD1." (PMID 26635092, 2015). "The proteolytic cleavage of macrophages CD100, mediated by OAEs MMP14, promoted pro-inflammatory responses in the airways, suggesting a potential mechanism of OAE-mediated asthma exacerbations." (PMID 38957448, 2024).
chondrosarcoma (7 papers, 2012 to 2023). A malignant cartilaginous matrix-producing mesenchymal neoplasm arising from the bone and soft tissue. "Similar to OS and ES, the expression of MMPs such as MMP-1, MMP-2, MMP-3, MMP-7, MMP-9, and MMP-14 is also found in biopsy specimens from patients with chondrosarcoma." (PMID 38138968, 2023). "In the case of studies and MMP-2 and MMP-14, the expression of this enzyme was confirmed in various molecular subtypes of chondrosarcoma: clear-cell chondrosarcomas, mesenchymal chondrosarcomas, conventional chondrosarcomas, and dedifferentiated chondrosarcomas." (PMID 38138968, 2023). "At the protein level, TIMP2 expression correlates with that of MMP2 and MMP14 in chondrosarcoma, all three proteins displaying elevated levels in high-grade anaplastic components compared to low-grade components of de-differentiated and conventional chondrosarcoma." (PMID 31466240, 2019). "For instance, in human chondrosarcoma cell lines that overexpress PEDF, MMP-14 levels were markedly low, and reduced trafficking of membrane-bound MMP-14 to the cell surface was observed, leading to decreased metastasis compared to matched controls." (PMID 26746675, 2016). "The expression of MMP-2 and MMP-14 was not significantly different between enchondroma and chondrosarcoma." (PMID 38138968, 2023). "By co-immunoprecipitation, we confirmed that FBXO6 could bind to MMP14 in both ATDC5 and SW1353 chondrosarcoma cell line." (PMID 32409323, 2020).
esophageal cancer (7 papers, 2014 to 2023). A primary or metastatic malignant neoplasm involving the esophagus. "Reduced expression levels of MMP-14 inhibit infiltration and proliferation of esophageal cancer, suggesting that MMP-14 and MMP-21 can mediate immune evasion of tumor cells through specific regulatory networks." (PMID 37359527, 2023). "Among the 28 known MMPs, MMP-1, MMP-2, MMP-9, MMP-10, MMP-14, and MMP-21 have been found to be closely associated with the metastasis and invasion of esophageal cancer." (PMID 37359527, 2023). "RKIP also inhibits esophageal cancer cell invasion via the downregulation of MMP-14 expression." (PMID 25435928, 2015).
influenza (7 papers, 2018 to 2023). An acute viral infection of the respiratory tract, occurring in isolated cases, in epidemics, or in pandemics; it is caused by serologically different strains of viruses (influenzaviruses) designated A, B, and C, has a 3-day incubation period, and usually lasts for 3 to 10 days. "Influenza infection induces the recruitment of myeloid cells expressing membrane type I matrix metalloprotease (MT1-MMP/MMP-14) that is important in lung development and homeostasis." (PMID 30619303, 2018). "Towards this end, a report found that inhibition of the collagenase MT1-MMP (MMP14) limited tissue damage and improved survival in a mouse model of severe influenza virus infection and in a model of influenza-pneumococcal coinfection." (PMID 31324202, 2019).
liver cancer (7 papers, 2021 to 2025). An epithelial or non-epithelial malignant neoplasm that arises from the liver. "Moreover, the mucin 15- (MUC15-) and MT1-MMP- (MMP14-) encoding genes are significantly related to capsule formation in liver cancer through the regulation of MMP2 expression." (PMID 34007838, 2021). "In a mouse liver cancer model, this increase in turn markedly increased MMP14 activity as well as tumour cell invasion and tumour expansion." (PMID 34279699, 2021). "In addition to the EMT regulated by Snail, nuclear Snail was also reported to play an another key role in regulating cell invasion by inducing increases in MMPs, such as MMP-1, MMP-2, MMP-7, MMP-9, and MMP-14, in ovarian, oral, and liver cancers." (PMID 36766694, 2023). "Because MMP14’s proteolytic activity is reliant on the addition of GalNAc, glycosylation of MMP14 is one mechanism by which GALA increases invasiveness in breast and liver cancer cells." (PMID 40098955, 2025).